SELP (selectin P)
Diseases named in the same sentence as SELP in open-access papers (continued):
Sharing a sentence is not in itself a finding about the gene and the disease.
type 2 diabetes (27 papers, 2007 to 2026). "Clinical studies have shown that higher SelP concentrations are associated with insulin resistance and type-2 diabetes, glycated A1C haemoglobin and fasting plasma glucose." (PMID 35204134, 2022). "Plasma SelP levels were reported elevated in patients with type 2 diabetes, and there was an association between high plasma selenium and fasting plasma glucose in type 2 diabetes patients." (PMID 36438755, 2022). "P-selectin, encoded by SELP, can capture leukocytes from the circulation to the vessel wall, leading to the rolling of neutrophils, and polymorphisms of SELP are associated with vascular risk of type 2 diabetes." (PMID 32377527, 2020). "So, SelP has been identified as a “hepatokine” that induces insulin resistance and excess SelP promotes type 2 diabetes." (PMID 36438755, 2022). "Considering that serum SelP levels are also elevated in people with type-2 diabetes compared with normal subjects, the study suggests that the secretory protein SelP could represent a target to develop new therapeutic strategies for the treatment of insulin resistance-associated diseases." (PMID 35204134, 2022). "Furthermore, qPCR of genes related to neutrophil activation revealed that the expression of SELL, SELP, CXCR1, and S100A8 was significantly increased in neutrophils from type 2 diabetes patients compared with that in neutrophils from controls." (PMID 32377527, 2020).
melanoma (26 papers, 1998 to 2025). A malignant, usually aggressive tumor composed of atypical, neoplastic melanocytes. "Despite being considered a T cell immune checkpoint, PSGL-1 has been shown to aid in the spreading and metastasis of melanoma and colon cancer cells via P-selectin (SELP) mediated platelet activation." (PMID 36497232, 2022). "Elevated levels of SELP have been observed in many cancers including melanoma, tongue, colon, gastric, lung and breast." (PMID 22937096, 2012).
coronary artery disease (25 papers, 2007 to 2025). "The absence of a positive correlation between OSM and ICAM-1, E-selectin and P-selectin may be caused by statin use in the AGES‐Reykjavik study (approx. 22%), as statins reduce ICAM-1, E-selectin and P-selectin plasma levels in patients with coronary artery disease." (PMID 31461490, 2019).
Hypertension (24 papers, 2008 to 2025). The presence of chronic increased pressure in the systemic arterial system. "Considering that the prevalence of T2DM (35%) and hypertension (57%) are highest in ACS patients versus healthy controls (10% and 29%, respectively), we performed a sub-analysis of the polymorphisms associated with a low risk of ACS (SELP Ser290Asn and SELP Thr715Pro)." (PMID 32053880, 2020). "Therefore, this analysis corroborates that the genetic variation of these polymorphisms of the SELP gene are associated to the ACS, and not comes of the T2DM or hypertension." (PMID 32053880, 2020).
colon carcinoma (20 papers, 2010 to 2025). "It has been demonstrated that SELP plays an important role in the growth and metastasis of human colon carcinoma in vivo." (PMID 34956309, 2021).
Obesity (20 papers, 2014 to 2025). Accumulation of substantial excess body fat. "SELP has also been proposed as a target therapy for metabolic syndrome, while increased levels of integrin beta 2 in adipose tissue and blood have been observed in diet-induced obesity." (PMID 40376303, 2025). "Similarly, pioglitazone treatment for 1 week reduced soluble P-selectin and P-selectin platelet expression in an insulin-resistant, obesity-prone KK mouse model." (PMID 34054542, 2021).
lupus (18 papers, 2014 to 2025). "The significance of the P-selectin-PSGL1 connection in the pathophysiology of SLE is demonstrated by the fact that inhibiting the P-selectin-PSGL1 axis with a monoclonal antibody to P-selectin causes a milder form of lupus-like illness." (PMID 39736771, 2024). "Only three non-coding SNPs of SELP i.e. rs3917657, rs2235302 and rs3917779, were previously found to be associated with systemic lupus erythematosus (SLE), carotid intima-media thickness and diabetic retinopathy." (PMID 32429899, 2020). "According to other studies, P-selectin polymorphisms play a role in the pathogenesis of systemic lupus erythematosus." (PMID 25541651, 2014). "Selectin P (SELP) was also upregulated (2-fold, p = 0.004) and is a cell adhesion protein upregulated in response to bacterial infections, delayed hypersensitivity reaction, T-cell lymphoma, and systemic lupus erythematosus." (PMID 33207582, 2020).
asthma (17 papers, 2011 to 2025). "Targeting this PSGL-1/P-selectin pathway has been proposed as a therapeutic strategy to reduce eosinophilic inflammation and mitigate asthma severity." (PMID 39518415, 2024).
sickle cell disease (17 papers, 2019 to 2025). Sickle cell anemias are chronic hemolytic diseases that may induce three types of acute accidents: severe anemia, severe bacterial infections, and ischemic vasoocclusive accidents (VOA) caused by sickle-shaped red blood cells obstructing small blood vessels and capillaries. "However, several studies have identified SELP as therapeutic target for several pathological conditions such as cardiovascular diseases and sickle-cell anemia." (PMID 33771989, 2021).
psoriasis (16 papers, 2014 to 2025). An autoimmune condition characterized by red, well-delineated plaques with silvery scales that are usually on the extensor surfaces and scalp. "Four genes (SELP, CD93, VAV1, and IL2RG) were identified as the most reliable diagnostic indicators for psoriasis." (PMID 40539722, 2025). "P-selectin-PSGL-1 binding is one of the factors which mediate the interaction between platelets and most leukocytes, including polymorphonuclear neutrophils (PMNs), monocytes/macrophages, and lymphocytes in psoriasis." (PMID 37654493, 2023).
rheumatoid arthritis (16 papers, 2012 to 2024). A chronic, systemic autoimmune disorder characterized by inflammation in the synovial membranes and articular surfaces. "At the same time, other reports have shown that the 715Pro (C) allele increased the expression of SELP mRNA, as well as the concentration of P-selectin levels in other inflammatory diseases, such as rheumatoid arthritis and T2DM." (PMID 32053880, 2020).
Hyperglycemia (15 papers, 2013 to 2024). An increased concentration of glucose in the blood. "Although there were some former pieces of evidence that miR-26b regulates SELP expression in hyperglycemia, we wanted to confirm the functional relationship between miR-26b and SELP mRNA under inflammatory conditions." (PMID 32013235, 2020).
acute coronary syndrome (12 papers, 2011 to 2025). Signs and symptoms related to acute ischemia of the myocardium secondary to coronary artery disease. "The aim of the present study was to evaluate whether the SELP gene single nucleotide polymorphisms (SNPs) are associated with presence of acute coronary syndrome (ACS) and with plasma P-selectin levels in a case-control association study." (PMID 32053880, 2020). "Activated platelets (P-selectin-positive platelets) express or release stromal cell-derived factor 1α (SDF-1α), leading to mobilization of bone marrow-derived CD34-positive cells into the peripheral blood in human acute coronary syndrome." (PMID 27374094, 2016).
glioblastoma (12 papers, 2017 to 2025). The most malignant astrocytic tumor (WHO grade IV). "In glioblastoma, cancer cells overexpress and oversecrete SELP to exploit PSGL-1 signaling in glioma-associated microglia/macrophages." (PMID 36497232, 2022). "Recent studies about SELP-PSGL-1 axis in glioblastoma found high expression in Selp-mRNA in microglia and secretion of Selp." (PMID 40684206, 2025). "For instance, studies indicate that glioblastoma overexpresses P-Selectin in the presence of microglia and that P-Selectin plays a role in glioblastoma proliferation and invasion when microglia are present." (PMID 39717751, 2024). "(D) Kaplan-Meier survival curves obtained from TCGA data of glioblastoma patients with high and low P-selectin expression (using 63 samples with top and bottom 10% of SELP expression)." (PMID 28976305, 2017). "To validate these findings, we looked at The Cancer Genome Atlas (TCGA) data analyzing the expression of P-selectin (SELP) in glioblastoma as well as other cancer types." (PMID 28976305, 2017). "We hence compared the expression levels of SELP gene in brain tissues obtained from three studies: healthy brain tissue from GTEx data (1259 samples) and lower grade glioma and glioblastoma from TCGA obtained from cBioPortal (530 and 578 samples, respectively)." (PMID 28976305, 2017).
lung carcinoma (12 papers, 2003 to 2026). "In the test cohort, 56 (36.8%) of 152 patients with NSCLC were stage I. The relative expression levels of ITGA2B and SELP mRNA remained improved when only stage I lung cancer detection was involved (p < 0.001)." (PMID 31523198, 2019). "In conclusion, the current study clearly reveals that the platelet derived mRNA, ITGA2B and SELP are significantly increased in primary lung cancer patients thus could discriminating NSCLC and controls, and the combination of ITGA2B and CEA even performs better." (PMID 31523198, 2019). "Conversely, seven of the downregulated hub genes (TLR4, PECAM1, SELP, CXCL12, VWF, KDR, and CD34) showed both low expression and good prognosis in lung cancer patients (p < 0.05)." (PMID 33627711, 2021).
glioma (11 papers, 2017 to 2025). A benign or malignant brain and spinal cord tumor that arises from glial cells (astrocytes, oligodendrocytes, ependymal cells). "SELP knockdown in glioma cells reduced proliferation and migration when co-cultured with microglia compared to controls." (PMID 35267626, 2022). "The interaction of glioma with microglia induces high expression of SELP and induces microglial polarization towards a pro-tumor phenotype through the SELP-PSGL-1 (P-selectin with P-selectin glycoprotein ligand-1) axis, enhancing their immunosuppressive capacity and promoting tumor progression." (PMID 37700840, 2023). "In the brain, selectin P (SELP) is widely expressed in glioma cells and contributes to tumor progression closely associated with its adhesion-modulatory function, whereas the soluble form (sSELP) mediates the suppression of resident and infiltrating macrophages." (PMID 34299113, 2021).
Insulin resistance (11 papers, 2014 to 2025). Increased resistance towards insulin, that is, diminished effectiveness of insulin in reducing blood glucose levels. "Under the condition of high glucose and insulin resistance, the dysregulated transcriptional activity of FoxO1 enhances the biosynthesis of SelP and gluconeogenic enzymes, which results in elevated plasma SelP and selenium levels and further elevated plasma glucose levels." (PMID 36438755, 2022). "Thus, from this point, elevated plasma SelP levels might be considered as the result rather than the cause of hyperglycemia and insulin resistance." (PMID 36438755, 2022).
malaria (11 papers, 2013 to 2024). Malaria is a serious and sometimes fatal disease caused by a parasite that commonly infects a certain type of mosquito which feeds on humans. "This is highly likely to be driven by host-pathogen co-evolution, such as to malaria parasites, as SELP is involved in the adherence of Plasmodium falciparum-infected erythrocytes to vascular-endothelial cells." (PMID 28419109, 2017). "P-selectin (SELP, also known as CD62P) is a host cell surface receptor protein that is known to influence malaria-associated pathology, both in human patients and rodent infection models." (PMID 26045295, 2015).
ovarian carcinoma (10 papers, 2010 to 2024). A malignant neoplasm originating from the surface ovarian epithelium. "The two metastatic ovarian cancer cell lines; SK-OV-3 [1.5×106 cells/ml, 47±10.2% of platelets P-selectin positivity, n = 3] and 59M [1.5×106 cells/ml, 51±18% P-selectin positivity n = 6] induced the most significant platelet activation." (PMID 22022533, 2011). "The lowest platelet activation was seen in response to the non-metastatic ovarian cancer cell line A2780 [1.5×106 cells/ml, 16.1±5.2% P-selectin positivity, n = 6]." (PMID 22022533, 2011).
Arterial thrombosis (9 papers, 2014 to 2025). The formation of a blood clot inside an artery. "The current model may have some applicability to core dynamics during TF-driven arterial thrombosis since the core thickness (thrombin and fibrin and P-selectin positive region) has been measured to be relatively similar between the venous (100 s-1) and arterial (2000 s-1) condition." (PMID 31381558, 2019).
cognitive decline (9 papers, 2014 to 2025). "SELP (Selectin P), another gene in this family, was found to be overexpressed in AD patients with fast cognitive decline and therefore, proposed as a prognostic biomarker and a potential target for treatment in a previous study." (PMID 37705610, 2023). "The biomarkers of platelet activation such as SELP and ITGA2B/glycoprotein IIb‐ITGB3/glycoprotein IIIa are increased in AD patients with faster cognitive decline compared with those with slow cognitive decline." (PMID 39757022, 2025).
pancreatic cancer (9 papers, 2014 to 2024). "Some studies have shown that the gene polymorphism of SELP could predict the risk of developing cachexia in pancreatic cancer." (PMID 37505298, 2024).
prostate carcinoma (9 papers, 2015 to 2025). A carcinoma that arises from epithelial cells of the prostate gland. "Conversely, findings from a cohort study encompassing 784 cases of prostate cancer and a corresponding control group indicated that the median plasma selenium levels and SelP concentrations were similar between the two groups, with a notable elevation in high-grade prostate cancer cases." (PMID 39839762, 2024). "SelP has also been suggested to be a biomarker for prostate cancer." (PMID 26452064, 2015).
venous thromboembolism (9 papers, 2014 to 2022). Occlusion of the lumen of a vein by a thrombus that has migrated from a distal site via the blood stream. "Previous studies suggested that various haplotypes of SELP polymorphisms may be established as the predictive marker in the etiology of various diseases including MI, CHD, SLE, venous thromboembolism, recurrent spontaneous abortions." (PMID 32429899, 2020).
endotoxemia (7 papers, 2004 to 2024). "In summary, we now demonstrate that MGBs can interfere in a targeted manner with HMGA1 binding to the P-selectin promoter in vivo, resulting in attenuated P-selectin induction and decreased lung and liver inflammation during murine endotoxemia." (PMID 20498830, 2010). "We describe a novel targeted approach in modulating lung and liver inflammation in vivo during murine endotoxemia through decreasing binding of HMGA1 to a distinct AT-rich region of the P-selectin promoter." (PMID 20498830, 2010).
hyperlipidemia (7 papers, 2014 to 2025). "SELP modulates thrombus formation through platelets activation, and a positive correlation has been observed between age and SELP expression in hyperlipidemia and thrombosis related diseases." (PMID 37662841, 2023).
myocardial ischemia (7 papers, 2013 to 2024). A disorder of cardiac function caused by insufficient blood flow to the muscle tissue of the heart. "In a mouse model of myocardial ischemia/reperfusion injury, salvianolic acid A exerted an anti-inflammatory effect by reducing serum levels of SELP and other cytokines." (PMID 38794213, 2024).
preeclampsia (7 papers, 2012 to 2025). Preeclampsia is a hypertensive disorder of pregnancy that is characterized by new-onset hypertension with proteinuria presenting after 20 weeks of gestation, and depending on mild or severe forms may initially present with severe headache, visual disturbances, and hyperreflexia. "Maternal platelet activation (P-selectin positive platelets) was linked with disease severity (sFlt-1/placental growth factor) and maternal plasma IL-1β and sVCAM-1 only in late-onset preeclampsia." (PMID 40746439, 2025).
acute pancreatitis (6 papers, 2009 to 2026). An acute inflammatory process that leads to necrosis of the pancreatic parenchyma. "Consequently, P‐selectin plays a pivotal role in thrombus formation by facilitating the aggregation of platelets and leukocytes on activated endothelial cells, thereby promoting the progression of acute pancreatitis." (PMID 41583122, 2026).
Arthritis (6 papers, 2005 to 2025). Inflammation of a joint. "Selectins are expressed in lymphoid, myeloid, and endothelial cells, and mice deficient in Selectin-P and selectin-E show an enhanced arthritis progression." (PMID 33879788, 2021). "In a SELP deficient mouse model of antigen-induced arthritis leukocyte-endothelial cell interaction was decreased." (PMID 25147926, 2014). "Additionally, a chemical compound acting as SELP antagonist efficiently reduced inflammation in the rat adjuvant induced arthritis model." (PMID 25147926, 2014).
heart failure (6 papers, 2015 to 2023). Inability of the heart to pump blood at an adequate rate to meet tissue metabolic requirements. "Abnormal surface SELP expression and soluble SELP levels have been reported in decompensated heart failure, suggesting persistent platelet activation." (PMID 31936828, 2020).
lymphoma (6 papers, 2001 to 2025). A malignant (clonal) proliferation of B- lymphocytes or T- lymphocytes which involves the lymph nodes, bone marrow and/or extranodal sites. "Finally, within CSF + LM group, differential protein profiles were observed between leukemia and lymphoma (such as FCGR1, CR2, ABL1, PTPRC, SELP, ITGB1, COL9A3 or ITGAX), which could subtype the CSF + LM depending on the primary tumor." (PMID 35053611, 2022).
leukemia (5 papers, 2013 to 2024). A malignant (clonal) hematologic disorder, involving hematopoietic stem cells and characterized by the presence of primitive or atypical myeloid or lymphoid cells in the bone marrow and the blood. "This suggests existence of multiple interaction mechanisms apart from P-selectin-PSGL interface that facilitate PMP uptake by leukemia cells." (PMID 31645903, 2019).
multiple sclerosis (5 papers, 2018 to 2023). A progressive autoimmune disorder affecting the central nervous system resulting in demyelination. "Indeed, It was reported that PSGL-1 levels in microglia were reduced in EAE model of multiple sclerosis, and reduced plasma levels of SELP and L-Selectin were detected in AD patients." (PMID 33771989, 2021).
periodontitis (5 papers, 2012 to 2025). An acute or chronic inflammatory process that affects the tissues that surround and support the teeth. "The intersection of these three machine learning approaches revealed six potential biomarkers associated with PANoptosis in periodontitis: PECAM1, CXCR4, SELP, IL2RG, CD48, and ZBP1." (PMID 40612110, 2025).
Alzheimer disease (4 papers, 2014 to 2024). A progressive, neurodegenerative disease characterized by loss of function and death of nerve cells in several areas of the brain leading to loss of cognitive function such as memory and language. "Moreover, SelP was found to be co-localized with both senile plaques and neurofibrillary tangles in the postmortem tissue from individuals with the hallmark lesions of Alzheimer’s disease (AD)." (PMID 24914767, 2014). "The exact mechanism that implicates SelP in Alzheimer’s disease has to be further investigated and discussed." (PMID 35204134, 2022). "The implications of the interaction between SelP and tubulin in the brain and in Alzheimer’s disease are discussed." (PMID 24914767, 2014).
autoimmune disease (4 papers, 2017 to 2025). A disorder resulting from loss of function or tissue destruction of an organ or multiple organs, arising from humoral or cellular immune responses of the individual to their own tissue constituents. "For instance, because P-selectin plays an important role in the pathogenesis of autoimmune diseases, Inclacumab, a novel monoclonal antibody against P-selectin, might be considered for the treatment of skin autoimmune diseases in future." (PMID 31333641, 2019).